RGN (regucalcin)
Diseases named in the same sentence as RGN in open-access papers (continued):
Sharing a sentence is not in itself a finding about the gene and the disease.
tumor (14 papers, 2014 to 2025). "Lower expression of regucalcin in human tumor tissue is associated with findings in patients with various types of cancer, including liver, pancreatic, breast, prostate, kidney, and colon cancer." (PMID 39858022, 2025). "In other cancer types, a relationship was also found between RGN and cell migration and invasion, further indicating that the loss of this protein accelerates tumour aggressiveness and progression towards metastasis." (PMID 39682121, 2024). "RGN expression was associated with preventive effects against the proliferation of tumor and progression of cancer cells." (PMID 37161020, 2023). "As an underlying mechanism, overexpressed regucalcin has been demonstrated to suppress tumor-related gene expression, such as c-myc, c-fos, c-jun, c-src or Ha-ras, which are tumor stimulator genes." (PMID 38001749, 2023). "Overexpressed regucalcin plays a critical role in suppressing cell growth by controlling various signaling processes associated with cell proliferation, repressing oncogene expression, and stimulating tumor suppressor gene expression in various types of human cancer cells." (PMID 38001749, 2023). "Overexpressed regucalcin plays a suppressive role in human cancer cell growth by suppressing various signaling processes associated with cell proliferation by repressing oncogene expression and stimulating tumor suppressor gene expression in various types of human cancer cells." (PMID 38001749, 2023). "Tissue microarrays have confirmed that the levels of regucalcin are decreased in HCC tissue compared to those in non-tumor tissue." (PMID 39858022, 2025). "The survival of colorectal cancer patients is prolonged with increased regucalcin gene expression in their tumor tissues." (PMID 39858022, 2025). "The survival time of cancer patients is prolonged with increased expression of regucalcin in the tumor tissues." (PMID 39858022, 2025). "In tumor and normal tissues of pan-cancer, mRNA expression of RGN was decreased significantly in seventeen types of cancer, including BLCA, BRCA, HNSC, LIHC, LUAD, LUSC, etc.." (PMID 37161020, 2023). "Results indicated that regucalcin expression was significantly reduced in NSCLC tissue compared to non-tumor tissue." (PMID 38001749, 2023). "Regucalcin was found to promote tumor dormancy through various mechanisms, including activation of p38 MAP kinase, decrease in Erk signaling, and inhibition of FOXM1 expression." (PMID 38001749, 2023). "Previous studies pointed out that RGN expression played a role in regulating various oncogenes and tumor suppressors by exerting growth suppressive effect." (PMID 37161020, 2023). "This study found that RGN expression was significantly downregulated in tumor tissues and closely related to clinical factors and prognosis of LUSC patients." (PMID 37161020, 2023). "Higher expression of regucalcin in tumor tissues has been demonstrated to extend the survival of cancer patients." (PMID 38001749, 2023). "RGN expression was closely associated with prognosis of LUSC patients and played an important role in tumor microenvironment." (PMID 37161020, 2023). "Regucalcin mRNA and protein expressions are significantly downregulated in tumor tissues of patients with various types of cancers." (PMID 38001749, 2023). "Intriguingly, RGN expression was at a lower level in tumor samples compared to normal samples, but our Kaplan–Meier survival curves demonstrated that LUSC patients with high RGN expression tended to have poor survival." (PMID 37161020, 2023). "For the first time, we discovered that RGN expression was significantly downregulated in tumor tissues compared with normal tissues and closely related to clinical factors and prognosis in LUSC patients according to TCGA and GEO databases." (PMID 37161020, 2023). "Regucalcin is a calcium-binding protein involved in calcium homeostasis and carbohydrate metabolism, and is recently reported as a newly identified tumour suppressor." (PMID 24523864, 2014).
tumor (continued). "Decreased expression of one of RGN's coexpression partner SELENBP1 which encodes a selenium-binding protein, has also been shown to be associated with multiple tumour types." (PMID 24523864, 2014). "The regucalcin expression is downregulated in RCC tumor tissue." (PMID 39858022, 2025). "Interestingly, the survival of patients with various types of cancer is prolonged with increased expression of regucalcin in the tumor tissues." (PMID 39858022, 2025). "The different responses observed between PNT1A and DU145 cells upon RGN downregulation highlight that RGN’s effects may depend on its intracellular levels, tumour status or relationship with other molecular targets." (PMID 39682121, 2024). "Our analysis revealed downregulation of regucalcin expression in RCC tumor tissues." (PMID 38001749, 2023). "Thus, elevated levels of regucalcin were demonstrated to obstruct tumor growth in mammary glands induced by carcinogens in vivo." (PMID 38001749, 2023). "Alternatively spliced variants of the regucalcin gene have been found in various normal and tumor tissues of human subjects, although they have not been observed in animals, including rats and mice." (PMID 38001749, 2023). "Regucalcin expression is downregulated in the tumor tissues of cancer patients." (PMID 38001749, 2023). "In the course of tumor development, RGN could exert complex biological cell functions and show antitumor activity." (PMID 37161020, 2023). "Patients exhibiting upregulated regucalcin in tumor tissue have shown prolonged survival." (PMID 38001749, 2023). "Our analysis implied that RGN may be important for regulating immune cell infiltration and activation in tumor microenvironment of LUSC, and further study was urged to investigate role of various immune cells and types in tumor microenvironment." (PMID 37161020, 2023). "Furthermore, regucalcin expression was found to be reduced in the tumor tissues of LUSC patients." (PMID 38001749, 2023). "However, the role of RGN and its specific mechanisms in the crafting of the tumor immunological microenvironment in LUSC remain unclear." (PMID 37161020, 2023). "Therefore, the identified down-regulation of RGN in PDAC may emphasize the tumor suppressor property of this protein." (PMID 33194391, 2020). "Finally, we performed IHC and qRT-PCR to evaluate the expression of RGN, and the results presented low RGN protein and mRNA expression level in LUSC tissues compared with adjacent non-tumor tissues." (PMID 37161020, 2023). "Conversely, WNK2, RUSC2, CYP3A4, and RGN, among the significantly downregulated genes in the non-tumor iP organoids, have been described as tumor suppressors downregulated in HCC." (PMID 34328417, 2021). "Additionally, a Kaplan–Meier survival analysis of tumor and normal tissues from 341 NSCLC patients showed that patients with lower regucalcin levels experienced worse overall survival in comparison with that of patients with a higher regucalcin expression." (PMID 39858022, 2025). "Therefore, we speculated the upregulated RGN with a worse prognosis in our research might be the result of regulation of high levels of HIF-α, especially in the hypoxic tumor microenvironment after tumor formation." (PMID 37161020, 2023).
cancer (12 papers, 2018 to 2025). A tumor composed of atypical neoplastic, often pleomorphic cells that invade other tissues. "The decrease of regucalcin expression is linked to the advancement of cancer." (PMID 38001749, 2023). "Diabetic states may cause a decrease in the regucalcin levels in the cancer cell microenvironment." (PMID 39858022, 2025). "Regucalcin has been shown to suppress the gene expression of cell-cycle-related proteins in proliferating cancer cells, including cdc2, cdk2m, chk2 (checkpoint kinase 2), and p21 mRNAs." (PMID 39858022, 2025). "This study proposes the involvement of extracellular regucalcin as a suppressor of cancer activity in the microenvironment." (PMID 39858022, 2025). "Alterations in these genes’ expression are reversed by the overexpression of regucalcin in cancer cells, resulting in cell growth retardation." (PMID 39858022, 2025). "This review will discuss the potential role of extracellular regucalcin in cancer cell activity as a critical suppressor in the cancer microenvironment." (PMID 39858022, 2025). "This review discusses the potential role of extracellular regucalcin in cancer cell activity as a potential suppressor in the cancer microenvironment, proposing the role of exogenous regucalcin in cancer prevention and therapy." (PMID 39858022, 2025). "Several studies performed in human cancer cell lines and rodents have demonstrated that RGN plays a significant role in controlling cell fate, namely in suppressing cell proliferation, migration and invasion." (PMID 39682121, 2024). "RGN knockdown induced a cancer-like phenotype in PNT1A cells, indicated by increased cell viability and proliferation and reduced apoptosis." (PMID 39682121, 2024). "Secreted POSTN can promote cancer stemness in head and neck cancer, and RGN promotes dormancy in cancer cells." (PMID 38200509, 2024). "Of note, there is increasing evidence that regucalcin plays a potential role as a suppressor in several types of human cancer." (PMID 38001749, 2023). "Overexpressed regucalcin has demonstrated its potential in suppressing the growth of human cancer cells." (PMID 38001749, 2023). "Regucalcin has been shown to suppress the proliferation of various cell types, including normal and cancer cells." (PMID 38001749, 2023). "In recent years, mounting evidence suggests that extracellular regucalcin suppresses the growth of various types of cancer cells." (PMID 38001749, 2023). "It is highly likely that the extracellular regucalcin produced within the tissues plays a vital role in inhibiting cancer cell growth." (PMID 38001749, 2023). "Extracellular regucalcin, which is increased in the cancer microenvironment, potentially suppresses carcinogenesis in various tissues." (PMID 38001749, 2023). "When diethylnitrosamine, a popular carcinogenic compound, is administered to RGN−/− mice, severe hepatic damage is observed, and, due to the high toxicity of this compound, all of the mice died before developing cancer." (PMID 36234722, 2022). "The cardiotoxic effects of doxorubicin, an anti-cancer agent that triggers the production of ROS, are enhanced in RGN−/− mice." (PMID 36234722, 2022). "In particular, regucalcin is a novel suppressor in several cancer types." (PMID 39858022, 2025). "This review outlines the role of intracellular regucalcin in cell regulation, signaling systems, and cell growth repression, and it discusses the inhibitory role of extracellular regucalcin on the cancer activity in various human cancer cells." (PMID 39858022, 2025). "Altered extracellular regucalcin may contribute to the progression of carcinogenesis and enhance the metastatic activity of cancer cells." (PMID 39858022, 2025). "In particular, regucalcin plays a role as a novel suppressor in several types of cancer patients." (PMID 39858022, 2025). "In particular, changes in serum regucalcin may influence the extracellular regucalcin levels in the cancer cell microenvironment." (PMID 39858022, 2025).
cancer (continued). "Downregulation of regucalcin gene expression in cancer cells may lead to stimulation of cell proliferation with alterations in the expression of various tumorigenesis-related genes." (PMID 39858022, 2025). "Reduced regucalcin in the kidneys may influence the levels of regucalcin in the tissue fluids of the cancer microenvironment, leading to the development of carcinogenesis and increased metastatic activity." (PMID 39858022, 2025). "Regucalcin is a potential suppressor of several types of human cancer." (PMID 39858022, 2025). "Reduced serum regucalcin may affect the extracellular regucalcin levels and contribute to cancer progression in the cancer microenvironment." (PMID 39858022, 2025). "Indeed, RGN has been shown to regulate multiple signalling pathways related to the hallmarks of cancer." (PMID 39682121, 2024). "This study first demonstrated that loss of RGN induces the development of cancer-like characteristics in non-neoplastic prostate cells and augments the aggressiveness of castration-resistant PCa cells." (PMID 39682121, 2024). "Moreover, this work investigated the putative interplay between GPER and RGN and its importance in modulating different cancer hallmarks." (PMID 39682121, 2024). "However, in vivo and in vitro studies have widely shown that RGN overexpression suppresses the proliferation of cancer cells." (PMID 39682121, 2024). "In addition, the downregulation of the regucalcin gene and its protein expressions in human cancer tissues has been demonstrated by multiple gene expression profiling and proteomics analyses." (PMID 38001749, 2023). "Downregulation of the regucalcin gene expression in cancer cells could lead to tumorigenesis with rapidly proliferating cells." (PMID 38001749, 2023). "Furthermore, regucalcin gene expression and protein levels are downregulated in human cancer tissues as per multiple gene expression profiling and proteomics analyses." (PMID 38001749, 2023). "This section delves into the role of extracellular regucalcin as a cancer cell suppressor." (PMID 38001749, 2023). "Additionally, the expression of regucalcin decreases in animals with cancer and contributes to the development of liver, prostate, and mammary gland carcinogenesis in in vivo animal models." (PMID 38001749, 2023). "Extracellular regucalcin may be a cytokine suppressing cancer cell growth." (PMID 39858022, 2025). "Regucalcin may hold a prominent role as a regulatory factor in cancer development." (PMID 38001749, 2023). "Supplying the regucalcin gene could prove to be a valuable asset in cancer treatment." (PMID 38001749, 2023). "Contrary to the previous genes, the products RGN, CAAP1, and STAP1, have been found to exert an anti-apoptotic effect and the disruption in their expression was reported in many cancers." (PMID 38978053, 2024). "Based on comparisons of RGN expression in pan-cancers, we summarized that LIHC, ACC, KICH, THCA and KIRP were the top 5 types of cancers with the highest expression." (PMID 37161020, 2023). "Of note, HAAO, MGLL, and UPGE were down-regulated in 18 cancer types; ADHFE1, CAT, and MSRA were down-regulated in 19; and RGN was down-regulated in 21 different types of cancer." (PMID 31351478, 2019). "RGN knockdown in an in vitro approach induced a cancer-like phenotype in non-neoplastic prostate cells and increased the aggressiveness features of PCa cells." (PMID 39682121, 2024). "Notably, the relationship between downregulation of RGN expression and cancer development is not exclusive to PCa." (PMID 39682121, 2024).
infection (5 papers, 2011 to 2025). The state of being infected such as from the introduction of a foreign agent such as serum, vaccine, antigenic substance or organism. "This phenomenon may explain why SFTSV in the patient’s blood comprises approximately 70% of rYG1 and 30% of rGn, which might be pathogenic variants in this fatal infection." (PMID 40202315, 2025). "E143K Natal RGN i.c. infection provoked relatively higher levels of CPE and EGFP signal in HMC3 cells compared to WT Natal RGN i.c., which was consistent with the results of TE671 and SF268 cells infected by E143K Natal RGN i.c and SRIP in comparison with WT and N139S Natal RGN i.c.s or SRIPs." (PMID 35891552, 2022).
adenocarcinoma (3 papers, 2014 to 2021). A common cancer characterized by the presence of malignant glandular cells. "A high expression of Survivin on the RNA level was negatively correlated with patients' survival in adenocarcinomas while a high Regucalcin expression was correlated positively." (PMID 31718698, 2019). "Within these, adenocarcinomas, smokers with low expression of Survivin show a better outcome, while the high expression of Regucalcin seems to be protective in never smokers." (PMID 31718698, 2019).
renal disease (3 papers, 2016 to 2025). "These include polycystic kidney disease-associated proteins (Pkd1, Pkd2), calcium/calmodulin-dependent protein kinases (Camk genes), and Regucalcin, but not randomly selected genes." (PMID 32457326, 2020). "Thus, the downregulation of regucalcin in the kidneys may lead to renal disease and carcinogenesis with altered extracellular regucalcin." (PMID 39858022, 2025).
metabolic disorders (1 paper, 2025). "Regucalcin plays a multifunctional role in cellular regulation in maintaining cell homeostasis and has been implicated in several metabolic disorders and diseases." (PMID 39858022, 2025).
RGN also shares sentences with these, for which no sentence is quoted: emphysema (4 papers); osteoporosis (3); scurvy (3); diabetes (2); Hepatic steatosis (2); liver cirrhosis (2); acute liver failure (1); adenoma (1); aging (1); Alzheimer disease (1); Atrophy (1); bacterial infections (1); carcinosarcoma (1); cardiac hypertrophy (1); cataract (1); Cirrhosis (1); corneal opacities (1); depression (1); dilated cardiomyopathy (1); Duchenne muscular dystrophy (1); dyslipidemia (1); embryonic carcinoma (1); endothelial dysfunction (1); glioma (1); Hyperglycemia (1); Hyperinsulinemia (1); ischemia (1); kidney damage (1); liver failure (1); liver fibrosis (1).
A further 6 diseases each share a sentence with RGN in 1 paper.